IFNG (interferon gamma)
Diseases named in the same sentence as IFNG in open-access papers (continued):
Sharing a sentence is not in itself a finding about the gene and the disease.
ovarian carcinoma (continued). "Splenocytes were subsequently tested for recognition of the mesothelin-expressing ovarian cancer cell line, SKOV3 and SKOV3 expressing HLA-A2 using an IFNγ ELISpot assay." (PMID 25933160, 2015). "Besides, TNFα coordinated with IFNγ to promote MUC16 (CA125) expression in breast and ovarian cancer via the NF-κB signaling axis." (PMID 38166970, 2024). "TNFα and IFNγ enhance MUC16 expression in breast, endometrial, and ovarian cancer cells through the NFκB pathway, with this upregulation linked to immune regulatory factor activity, indicating that MUC16 modulation may benefit treatment." (PMID 38361923, 2024). "However, epigenetic silencing of CCL5 expression through DNA methylation in ovarian cancer cells leads to the TIL desertification and reduced IFNγ polarized M1 TAMs." (PMID 36035994, 2022). "Moreover, CXCR4, IFNG, IL24, MTMR14, and RB1 all exhibited higher expression in ovarian cancer compared to normal specimens." (PMID 33748162, 2021). "Furthermore, IFNG, IL24, MTMR14, and RB1 were highly expressed in ovarian cancer than normal tissues." (PMID 33748162, 2021). "Further, we showed that IFNγ treatment as well as DNMT inhibition may overcome such epigenetic regulation and increase HLA-A expression in selected ovarian cancer cells." (PMID 33149148, 2020). "Curiously, ovarian cancer cells have been shown to be capable of inducing the IRE1α-XBP1 arm in T cells to decrease their anti-tumor activity via suppressing mitochondrial respiration and interferon gamma (IFNγ) production." (PMID 31491919, 2019). "IFNγ is a potent activator of myeloid cells inducing the generation of immunostimulatory M1 and, as previously observed, preventing the generation of TAM-like in ovarian cancer." (PMID 23409120, 2013). "Additionally, studies show that inflammatory cytokines TNFα and IFNγ can stimulate MUC16 expression in breast cancer, endometrial cancer, and ovarian cancer cells via NFκB, and in these cancer tissues, increased MUC16 expression is associated with elevated cytokine levels." (PMID 38361923, 2024). "Monthly vaccination of 6 breast/ovarian cancer patients having HER2/neu-overexpressing tumors with HER2/neu-derived HLA-A2-peptide and GM-CSF as adjuvant, for six months was found to induce interferon-gamma (IFN-γ) secreting CD8+ T lymphocytes targeting HER2/neu." (PMID 37513965, 2023). "Similarly, IFNγ is not used for the treatment of multiple sclerosis and although IFNγ has shown some benefit in the treatment of ovarian cancer it is has had not been widely used to treat neoplastic disease." (PMID 27713294, 2010). "Interestingly, although the combination of TNFα and IFNγ could induce the production of CCL5 in ovarian cancer ascites cells or macrophages, their joint blockade did not abrogate induction of CCL5 in co-cultures of activated CD8+ T cells with ascites cells or myeloid cells." (PMID 41142824, 2025). "Similar enhancement of activation and IFNγ production with mbIL12 was shown against human patient-derived TAG72+ gastric and ovarian cancer ascites cells, with little to no impact on the targeting of normal primary human cells." (PMID 37550294, 2023).
colorectal cancer (237 papers, 1996 to 2026). A primary or metastatic malignant neoplasm that affects the colon or rectum. "High expression of NKG2D and genes associated with an IFNγ signature are associated with decreased survival in a subset of colorectal cancer patients." (PMID 36980678, 2023). "To understand the mechanism resulting in IFNγ-mediated tumor progression, we used a mouse model of colorectal cancer where we previously showed that NKG2D-deficiency improved survival." (PMID 36980678, 2023). "High IFNG expression is correlated with both PD-L1 and PD-1 expression and associates with better colorectal cancer prognosis." (PMID 37002343, 2023). "Mutations in the components of the IFNγ signaling pathway have been reported in multiple types of human cancer, including colorectal cancer." (PMID 34385592, 2022). "On the contrary, IFNG is higher expressed in the left-colorectal cancer high-risk group, while Aloxe3 is more highly expressed in the right-colorectal cancer high-risk group." (PMID 35265525, 2022). "Usually, IFNγ expression is associated with a superior outcome in most cancer entities, such as colorectal cancer." (PMID 32100077, 2020). "Colorectal cancer has been particularly well studied, with several laboratories showing a positive association between patient survival and effector (IFNγ+) T cell infiltration into the tumour." (PMID 21864372, 2011). "Interestingly, high IFNγ expression correlated with high STAT1 or CD274 expression in colorectal cancer, but high CBX3 expression was significantly associated with low expression levels of STAT1 or CD274." (PMID 38684864, 2024). "In conclusion, we provide an analysis of the patterns and dynamics of class II induction in colorectal cancer and the epigenetic marks that underlie them, using an in vitro patient-derived organoid model system and IFNγ, the crucial microenvironmental cytokine." (PMID 37565053, 2023). "The loss of IFNγ signaling gene expression has been observed in patients with colorectal cancer." (PMID 34385592, 2022). "Different species of Lactobacillus inhibit the production of interleukin-8 and interferon gamma, attenuating inflammation in gastric epithelial cells and inhibit the adhesion of the bacterium H. pylori, linked to the initiation of gastric and colorectal cancer." (PMID 36017495, 2022). "Indeed, a recent transcriptome analysis of 585 human colorectal cancer samples revealed that tumor infiltration by IFNγ-producing Vδ2+ T-cells in particular was associated with higher probability of 5-year disease-free survival." (PMID 29867962, 2018). "Thus, while it is evident that JAK1, JAK2, and B2M mutations can contribute to immune resistance in multiple types of cancer, the loss of IFNγ signaling gene expression may be the predominant source of ICB resistance in colorectal cancer." (PMID 34385592, 2022). "According to survival analysis of core genes, colorectal cancer patients with high levels of IFNG, MMP9, and IL1B expression are likely to have shorter survival times." (PMID 40868987, 2025). "The plasma levels of several cytokines (interleukin-1β /IL-1β/, IL-2, IL-4, IL-10, IL-12, IL-15, TGFβ and IFNγ) of 20 patients with colorectal cancer and 21 healthy individuals were determined by ELISA." (PMID 39456247, 2024). "Upregulation of CysLT1, which enhances Wnt/β-catenin signaling, led to endogenous and IFNγ-induced PD-L1 expression in colorectal cancer cells." (PMID 38341410, 2024). "Our work identifies an interplay between CBX3 and IFNγ signaling that leads to regulation of the immune response in colon epithelium and of chemo-resistance of colorectal cancer." (PMID 38684864, 2024).
colorectal cancer (continued). "CBX3 appears as a potential target to enhance IFNγ-related therapeutic efficacy in UC and in colorectal cancer." (PMID 38684864, 2024). "A strong connection was discovered between PD-L1 and IFNγ, as well as elevated levels of both PD-L1 and IFNγ, along with miR-93-5p, in samples taken from both the tumor and margin areas of colorectal cancer." (PMID 38462628, 2024). "Previous studies demonstrated that a proportion of colorectal cancer cell lines cannot be induced to express class II upon IFNγ treatment." (PMID 37565053, 2023). "IFNγ is typically an indicator of good prognosis in colorectal cancer, yet studies have suggested that low concentrations of IFNγ can negatively impact the anti-tumor response, whereas high levels lead to tumor regression." (PMID 36980678, 2023). "The genetic variations in interferon-gamma (IFN-γ) and its receptor (IFN-γR) subunits are strongly associated with the risk of colorectal cancer and patient survival after diagnosis." (PMID 37176567, 2023). "We present an analysis of tsMHC-II inducibility in a series of 15 colorectal cancer organoids, focusing on the cancer cell-autonomous mechanisms restricting class II expression via in vitro IFNγ stimulation." (PMID 37565053, 2023). "Using model in vitro systems that reproduce the promoter methylation of their tissue of origin, we show that, providing IFNγ signaling is intact, the majority of colorectal cancer organoids are class II inducible." (PMID 37565053, 2023). "In the first such study, we analyze patterns, dynamics, and epigenetic control of IFNγ-induced class II expression in a series of colorectal cancer organoids." (PMID 37565053, 2023). "The aim of this study was to elucidate the molecular mechanisms through which IFNγ alters HLA-I peptide presentation by comparing the immunopeptidome of untreated and 48-hour IFNγ-treated colorectal cancer PDOs (CRC-01, CRC-04, CRC-05)." (PMID 37991387, 2023). "In colorectal cancer, KRAS mutation suppresses Th1/CTL immunity, reducing IFNγ and CXCL10 production, therefore decreasing CTL infiltration." (PMID 36311166, 2022). "Strategies that enhance IFNγ signaling are a rational and novel approach for the management of colorectal cancer patients." (PMID 34385592, 2022). "A pivotal study in colorectal cancer identified that intratumoral eosinophils exert these anti-tumorigenic effects through interferon-gamma (IFNγ) signaling." (PMID 35563461, 2022). "Similar but more potent results were obtained with the HT29 colorectal cancer cell line, where a combined treatment of IFNγ with tryptophan depletion showed an especially strong W>F substitution presentation and T cell recognition." (PMID 35264796, 2022). "In the colorectal cancer microenvironment, tumor-infiltrating effector T cells and natural killer (NK) cells are the primary sources of IFNγ." (PMID 34385592, 2022). "In this review, we summarize recent advances in the epigenetic, genetic, and functional integrity of the IFNγ signaling pathway in the colorectal cancer microenvironment and its immunological relevance in the therapeutic efficacy of and resistance to ICB." (PMID 34385592, 2022). "In some tumor types such as ovarian, prostate, and colorectal cancer, Th17 cells induce an antitumor immune response by recruiting cytotoxic effector T cells and producing effector cytokines, including interferon-gamma." (PMID 35186032, 2022). "GBP1 functions as a tumor suppressor in colorectal cancer, and in contrast, can protect prostate carcinoma cells from IFNγ-mediated apoptosis." (PMID 36187937, 2022). "IFNγ is a potent inducer of IDO expression, which serves as a pathogenic driver of colorectal cancer progression." (PMID 34385592, 2022). "Given the importance of the IFNγ signaling pathway in tumor immunity and immunotherapy, in this review, we summarize our current understanding of the IFNγ signaling pathway in colorectal cancer and discuss potential novel therapeutic approaches." (PMID 34385592, 2022).
colorectal cancer (continued). "In summary, IFNγ can be expressed by multiple immune cell subsets in the colorectal cancer microenvironment." (PMID 34385592, 2022). "New clinical applications stem from scientific breakthroughs via basic research and discovery, and a deeper understanding of IFNγ signaling pathway integrity in colorectal cancer microenvironments is critical." (PMID 34385592, 2022). "Consistent with other studies, we showed that IFNγ can upregulate CEA levels on colorectal cancer cell lines." (PMID 36405739, 2022). "New insights into the genetic, epigenetic, and metabolic regulation of IFNγ signaling will pave the way for new clinical trials and novel immune-based therapies for patients with colorectal cancer." (PMID 34385592, 2022). "Epigenetic histone modifications by polycomb repressive complex 2 (PRC2) and SWItch/Sucrose Non-Fermentable (SWI/SNF) complexes are involved in the regulation of the IFNγ signaling pathway in colorectal cancer." (PMID 34385592, 2022). "Conversely, ARID1A (BAF250A), a core member of the SWI/SNF complex, supports CXCL9 and CXCL10 expression in human colorectal cancer cells, resulting in enhanced recruitment of IFNγ-producing immune cells." (PMID 34385592, 2022). "Despite the fact that Tregs suppress the cancer immune response via multiple pathways, Tregs also express IFNγ, and IFNγ+ Tregs remain immunologically suppressive in the human colorectal cancer microenvironment." (PMID 34385592, 2022). "In our study, IFNg mRNA levels increased in tumor tissues and peripheral blood samples of colorectal cancer group compared to the control group." (PMID 33237662, 2021). "Studies to clarify the effect of IFNg on the colorectal cancer process are very new and future studies are needed." (PMID 33237662, 2021). "We extended our analysis to other human cancer datasets and found a significantly positive correlation between the neutrophilic infiltrate, IFNG expression, a type 1 immune response gene signature and better prognosis in colorectal cancer (CRC)." (PMID 31257026, 2019). "The relatively low level of IFNγ in colorectal carcinoma xenografts correlated well with the high proportion of immigrated angiogenic monocytes." (PMID 29367702, 2018). "All colorectal cancer cell lines tested produced CXCL11 after stimulation with the cytokines IFNγ and TNFα, as evidenced by qRT-PCR and by ELISA." (PMID 29163806, 2017). "A recent study indicated that a vicious cycle involving the CXCR3-CXCL10 axis and IFNγ operates in colorectal carcinoma progression." (PMID 22408433, 2012). "In fact, within our colorectal cancer patient group we noted alterations in the IFNγ pathways in men and IL-6 in women and persistence of IL-10 under both resting and activated conditions." (PMID 22235223, 2011). "Furthermore, reduced FABP1 expression has been documented in MSI-high (microsatellite instability-high) colorectal cancers, potentially attributable to the IFNγ-mediated suppression of PPARG within their highly immunoreactive microenvironment." (PMID 40694956, 2025). "To test this hypothesis, we treated MSI colorectal cancer cell lines with IFNγ, which strongly induced PD-L1 expression in most cell lines, except for RKO cells, which constitutively expressed high levels of endogenous PD-L1." (PMID 40824763, 2025). "Furthermore, they demonstrated the synergistic efficacy of indirect CAP with IFNγ in inducing colorectal cancer cell ferroptosis via the same axis, suggesting a potential innovative approach for treating colorectal cancer." (PMID 39438918, 2024). "In consistent with this, ionizing radiation was shown capable of resolving the tumor burden in wildtype mice, but did not arrest tumor growth when the gene encoding IFNγ was knocked out using a murine colorectal cancer model." (PMID 37671945, 2023). "Providing IFNγ signaling is intact, most colorectal cancer organoids are class II inducible." (PMID 37565053, 2023).
colorectal cancer (continued). "We performed proteomic analyses of untreated and IFNγ-treated colorectal cancer patient-derived organoids and combined this with transcriptomic and HLA-I immunopeptidomics data to dissect mechanisms that lead to remodeling of the immunopeptidome through IFNγ." (PMID 37991387, 2023). "Hence, different T-cell subsets can express IFNγ, thereby altering the immune responses in the colorectal cancer microenvironment." (PMID 34385592, 2022). "Thus, targeting IFNγ-induced intrinsic immunosuppressive mechanisms should be explored in patients with colorectal cancer." (PMID 34385592, 2022). "The relative contribution of each cell type to the total levels of IFNγ may depend on the quantity and quality of each immune subset within the tumor and is likely subject to multiple layers of regulation in the colorectal cancer microenvironment." (PMID 34385592, 2022). "Moreover, we discuss how to target IFNγ signaling to inform novel clinical trials to treat patients with colorectal cancer." (PMID 34385592, 2022). "In the late stage of colorectal cancer, ILC1s are decreased and produce less IFNγ." (PMID 34385592, 2022). "In addition, we and others have shown that IFNγ can upregulate CEA levels on colorectal cancer cell lines, similarly to the effect of 5-FU boosting CEA and TCE binding." (PMID 36405739, 2022). "Thus, loss of optineurin impairs the integrity of the IFNγ- and MHC-I-signaling pathways via IFNGR1 degradation, thereby driving immune evasion and intrinsic immunotherapy resistance in colorectal cancer." (PMID 34385592, 2022). "Given that colorectal cancer patients exhibit infrequent IFN- and MHC-signaling gene mutations and are generally resistant to ICB, a recent study has explored alternative mechanisms that may constrain IFNγ signaling in colorectal cancer." (PMID 34385592, 2022). "In particular, in contrast to the scarcity of epitopes with amino acid substitutions arising from genetic mutations, a substantial enrichment of W>F substitutants was observed in the immunopeptidome of IFNγ-treated microsatellite stable colorectal cancer organoids." (PMID 35264796, 2022). "In addition to providing energy for the colonocytes, butyrate can suppress NF-κB transcription factor activation and interferon gamma and upregulate PPARγ, which thus withstand colorectal cancer and inflammatory bowel diseases." (PMID 33922589, 2021). "IFNg mRNA level was upregulated in both colorectal cancer tumor tissues and peripheral blood." (PMID 33237662, 2021). "Compelling additional evidence corroborated the existence of close interactions between the tumor endothelium and immune effectors cells with therapeutic implications for ICIs treatment in a colorectal cancer model in an interferon gamma (IFNγ)-dependent fashion." (PMID 33203154, 2020). "This suggests that IFNγ also found at low level in human colorectal cancer samples, might have a deleterious action on HPMo recruitment by causing their continuous crawling on the endothelial surface." (PMID 29367702, 2018). "The upregulated response to IFNγ, inflammation response, immune and chemokine mediated signaling pathways demonstrate that inflammation is a major feature of the tumor microenvironment in colorectal cancer." (PMID 29088818, 2017). "In addition, significant alterations in the IFNγ and IL-6 gender-specific pathways and IL-10 gender-common pathways were found in colorectal cancer patients." (PMID 22235223, 2011). "Since colorectal cancer is a significant contributor to the expression of PD-L1, IFNγ, and miR-93-5p, by comprehending the mechanisms that drive PD-L1 expression within the tumor, new prospects may emerge for focused immunotherapy in the treatment of CRC (p values < 0.05)." (PMID 38462628, 2024). "Thus, it is worth to verify experimentally whether the IFNγ/IFNGR2/APC/TCF4/GPX4 axis exists in colorectal cancer cells that, once taking on actions, triggers ferroptosis in colorectal CSCs." (PMID 37671945, 2023).